HNF1B (HNF1 homeobox B)
Diseases named in the same sentence as HNF1B in open-access papers (continued):
Sharing a sentence is not in itself a finding about the gene and the disease.
kidney tumors (5 papers, 2013 to 2023). "The study further confirms the role of HNF1B expression in renal neoplasms and its potential as a diagnostic marker for Chromphobe renal cell carcinoma." (PMID 33580750, 2021). "Notably, by combining the cohorts of gynecologic and renal neoplasms (n = 141), HNF1B positivity was associated with a strongly significant 2.3-fold increased risk of thromboembolism (P = 0.011; two-tailed Fisher’s exact test)." (PMID 24040285, 2013). "Overall, these apparently contradictory findings confirm the multifaceted role of HNF1B in kidney tumor development and support the need for broader analysis and validation studies." (PMID 36672242, 2023). "We have performed a comprehensive, multi-level analysis of the HNF1B gene on several of the most common kidney tumour subtypes." (PMID 33051485, 2020). "The results of the IHC staining analysis revealed that there were significant differences in the presence and intensity of HNF1B expression among the four analysed subsets of kidney tumours (p < 0.001)." (PMID 33051485, 2020). "In renal tumors, HNF1B positivity showed a trend towards increased thromboembolic events (P = 0.14, two-tailed Fisher’s exact test)." (PMID 24040285, 2013). "In contrast, the expression of HNF1B per se in kidney tumors has been widely explored and its immunohistochemical evaluation was proposed to differentiate renal oncocytoma (diffusely and strongly positive, nuclear stain) from chromophobe renal cell carcinoma (negative)." (PMID 36672242, 2023). "However, in order to determine the precise role of HNF1B in kidney tumour biology and its potential prognostic and therapeutic application, more studies on larger cohorts are needed." (PMID 33051485, 2020). "We have performed a comprehensive, multi-level analysis of HNF1B in several different kidney tumour types and found that the genetic and epigenetic analyses did not reveal any HNF1B mutations and only rare promoter methylation." (PMID 33051485, 2020). "In total, we observed HNF1B expression in 66% of gynecologic and 56% of renal neoplasms with cytoplasmic clearing, compared to 5% and 16%, respectively, without cytoplasmic clearing, and compared to 1% of other neoplasms, all highly significant differences (P<0.001; two-tailed Fisher exact tests)." (PMID 24040285, 2013). "However, the effects of HNF1B somatic exonic mutations and its role in the pathogenesis of kidney tumours has not yet been elucidated." (PMID 33051485, 2020). "Therefore, our aim was to perform a comprehensive analysis of the expression, epigenetic, and genetic changes of HNF1B in kidney tumours, and to further investigate its potential differential diagnostic, prognostic and therapeutic value, mainly at the level of somatic changes." (PMID 33051485, 2020).
liver cancer (5 papers, 2013 to 2021). An epithelial or non-epithelial malignant neoplasm that arises from the liver. "In this study, we found that HNF-1β expression was associated with the pathologic subtype of primary liver cancer, with high expression in ICC and significantly lower expression in HCC." (PMID 28684878, 2017). "The invasion ability and epithelial-mesenchymal transition (EMT)-associated genes were also significantly higher in liver cancer cells overexpressing HNF-1β than in the control group." (PMID 28684878, 2017). "Our previous study showed that HNF-1β expression was associated with a pathological subtype of primary liver cancer." (PMID 28684878, 2017). "The main findings of our study were that HNF-1B expression was associated with the pathologic subtype of primary liver cancer, and HNF-1B expression in HCC tissue may be associated with the change of phenotype on recurrence." (PMID 26311117, 2015). "Therefore, we hypothesized that as a biliary marker, HNF-1B expression in primary liver cancer would be associated with HPC markers expression and predict a poorer outcome." (PMID 26311117, 2015). "We retrospectively reviewed the liver tumour tissue specimens collected from 90 liver cancer patients and analysed the correlation between the prognosis and the HNF-1β expression level." (PMID 28684878, 2017). "Overall, HNF-1β maintains the stemness of liver cancer cells by regulating the Notch signalling pathway and EMT, thereby enhancing the invasion and metastasis of liver cancer and worsening the prognosis of liver cancer patients." (PMID 28684878, 2017). "We overexpressed HNF-1β in liver cancer cell lines and found the expression of liver progenitor cell markers and stemness were upregulated." (PMID 28684878, 2017). "In recent years, the importance of HNF-1β in liver cancer diagnosis and prognosis has been gradually recognized." (PMID 28684878, 2017). "Comparing HNF-1B expression in HCC with ICC, we found that the level of HNF-1B expression was lower in HCC patients than in ICC patients, which indicates that HNF-1B is associated with the pathologic subtype of primary liver cancer." (PMID 26311117, 2015). "We investigated HNF-1B expression in different pathologic subtypes of primary liver cancers, and the relationship between HNF-1B expression and HPC/biliary markers expression by means of immunohistochemistry." (PMID 26311117, 2015). "HNF1β can be used as an important predictor of poor prognosis of liver cancer." (PMID 35096588, 2021). "We found that liver cancer patients with increased HNF-1β expression had elevated stemness." (PMID 28684878, 2017). "Furthermore, the expression of HNF-1β was positively correlated with the prognosis of the liver cancer patients." (PMID 28684878, 2017). "So far, the study of HNF-1B and liver cancer is still limited." (PMID 26311117, 2015). "In conclusion, we found that in patients with primary liver cancer, the expression of HNF-1B was related to different pathologic subtypes of primary tumor, and HNF-1B expression in HCC tissue may be associated with the change of phenotype on recurrence." (PMID 26311117, 2015). "Therefore, we considered whether HNF-1β influenced the prognosis of patients with liver cancer." (PMID 28684878, 2017). "Overall, research on the effect of HNF-1β on the maintenance of stemness in HCC cells and its mechanism could provide a useful target for prognostic prediction in HCC and provides a potential target for effective treatment of patients with primary liver cancer." (PMID 28684878, 2017).
liver disease (5 papers, 2022 to 2024). "From this perspective, we are generating both an animal model of HNF1B-KO mouse and mouse organoids to understand the pathophysiology of liver disease associated with perturbations in the HNF1B signaling pathway." (PMID 36672242, 2023). "Critical homeobox nuclear factor family members that are normally downregulated in severe liver disease such as Hnf4a and Hnf1b were, however, unchanged." (PMID 36232721, 2022). "Liver disease in NAIC overlaps with the hepatic component of Alagille syndrome (AGS; OMIM #118450), an autosomal dominant disease caused by mutations in the notch signaling effectors JAG1 or NOTCH2 or the transcription factor HNF1B." (PMID 36656901, 2023). "Presence of unexplained liver disease increases the degree of suspicion for HNF1B-MODY." (PMID 36793123, 2023).
lung adenocarcinoma (5 papers, 2018 to 2023). A carcinoma that arises from the lung and is characterized by the presence of malignant glandular epithelial cells. "TTF-1 and Napsin A were expressed in all 7 cases, and metastatic lung adenocarcinoma was further supported with the negative results for PAX8, HNF-1β, ER and PR, and history of lung adenocarcinoma." (PMID 31455365, 2019).
ovarian tumors (5 papers, 2010 to 2023). "In ovarian tumors, expression of HNF1β was associated with E-cadherin." (PMID 21975049, 2011). "In this study, which was performed on 279 ovarian tumors, the expression of HNF1β, Napsin A, and AMACR markers in 65 cases of CCC was obtained at 92%, 82%, and 63%, respectively." (PMID 37383161, 2023). "Methylation of the HNF-1β gene promoter was found in some cancer cell lines derived from pancreatic, colorectal, gastric, and ovarian tumors." (PMID 25884453, 2015).
Alport syndrome (4 papers, 2021 to 2026). A rare renal disease characterized by glomerular nephropathy with hematuria progressing to end-stage renal disease (ESRD), frequently associated with sensorineural deafness, and occasionally with ocular anomalies. "In addition, this review also summarizes the findings of ncRNAs in other common monogenic kidney diseases, including HNF1β-associated kidney disease, Alport syndrome, congenital abnormalities of the kidney and urinary tract (CAKUT), von Hippel–Lindau (VHL) disease, and Fabry disease." (PMID 33809516, 2021).
autism spectrum disorder (4 papers, 2023 to 2025). A spectrum of developmental disorders that includes autism, and Asperger syndrome. "Several studies suggest that in general, patients with genetic variation of HNF1B have an elevated risk for additional neurodevelopmental disorders, especially autism spectrum disorder (ASD) but a comprehensive assessment is yet missing." (PMID 36969268, 2023).
bladder cancer (4 papers, 2015 to 2026). "Functionally, knockdown of HNF1B promoted bladder cancer cell proliferation, migration, and invasion, whereas its overexpression suppressed these malignant phenotypes in vitro and attenuated tumor growth in vivo." (PMID 41723508, 2026). "However, higher levels of HNF1B indicated better overall survival in bladder carcinoma (HR=0.5, p=4.5e-06), kidney renal papillary cell carcinoma (HR=0.35, p=0.00032), (HR=0.37, p=0.04), and uterine corpus endometrial carcinoma (HR=0.58, p=0.0095)." (PMID 33173410, 2020).
Cholestatic liver disease (4 papers, 2019 to 2025). "Mutations or deletions of the HNF1β gene have been described in correlation with different hepatic phenotypes, including NC, adult-onset cholestasis, non-cholestatic liver disease, and, more recently, pediatric hepatocellular carcinoma." (PMID 40256398, 2025). "Although genetic tests for liver cholestatic diseases were performed with negative results for Alagille syndrome (JAG1 and NOTCH2), a de-novo missense mutation of HNF1β gene was detected." (PMID 30791938, 2019). "Liver involvement in HNF1B-related conditions has not been extensively studied, with reported cases mainly presenting as an asymptomatic elevation in transaminase levels or, less commonly, as cholestatic liver diseases." (PMID 39337310, 2024). "Moreover, these new drugs already applied to other types of PFIC and cholestatic liver disease, could be considered in children and adults with KIF12 and HNF1B defective function." (PMID 36672242, 2023).
diabetic nephropathy (4 papers, 2015 to 2025). "Renal mRNA levels of transporters were reduced with diabetic nephropathy in females and the expression of transcription factors Hnf1β and Hnf4α in both sexes." (PMID 25710042, 2015).
hydronephrosis (4 papers, 2019 to 2025). Collection of urine in the renal pelvis that results in dilatation of the renal pelvis and calyces. "Hydronephrosis/hydroureter have been also described in RCAD patients as well as in different mouse models with Hnf1b inactivated in the collecting ducts." (PMID 33737325, 2021).
Impaired glucose tolerance (4 papers, 2016 to 2024). An abnormal resistance to glucose, i.e., a reduction in the ability to maintain glucose levels in the blood stream within normal limits following oral or intravenous administration of glucose. "MiR-802 was described to be upregulated in the liver of obese human patients and to target hepatocyte nuclear factor 1-beta (Hnf1b), where reduction was related to impaired glucose tolerance and reduced insulin sensitivity." (PMID 31207998, 2019).
insulinoma (4 papers, 2017 to 2023). "Overexpression of either HNF1α or HNF1β induces ACE2 mRNA levels in mouse pancreatic islet cells and rat insulinoma cells." (PMID 37608279, 2023). "Our predictions, for HNF1A and HNF1B factors, have been formerly reported experimentally to drive ACE2 expression in pancreatic islet cells and insulinoma cells, respectively." (PMID 33244381, 2020). "Two of our predictions, for HNF1A and HNF1B, have been previously identified experimentally to drive ACE2 expression in pancreatic islet cells and insulinoma cells, respectively." (PMID 33112891, 2020).
lung carcinoma (4 papers, 2020 to 2024). "Our finding that lower expression of HNF1B is linked to many inactivated enhancers in LUAD suggests that it may also act as a tumor suppressor in lung cancer." (PMID 32925947, 2020).
multicystic dysplastic kidney (4 papers, 2012 to 2022). Multicystic dysplastic kidney (MCDK) is a congenital anomaly of the kidney and urinary tract (CAKUT) in which one or both kidneys (unilateral or bilateral MCDK respectively) are large, distended by multiple cysts, and non-functional. "Four patients had a deletion or duplication of chromosome 17q12 containing HNF1B with variable renal manifestations including renal hypodysplasia, multicystic dysplastic kidney, vesicoureteral reflux, ureteral obstruction, and renal cortical cysts." (PMID 32164334, 2020). "Renal phenotypes of mutations in HNF1B, PAX2, and EYA1 were bilateral renal hypodysplasia or unilateral renal hypodysplasia with contralateral multicystic dysplastic kidney." (PMID 32164334, 2020). "For example, we developed a disease model for multicystic dysplastic kidney (MCDK) using our iUB organoids and heterozygous HNF1β-knockout hiPSC lines established by the CRISPR-Cas9 system." (PMID 35769929, 2022).
Multiple renal cysts (4 papers, 2022 to 2026). The presence of many cysts in the kidney. "In this report, we describe a 12-year-old Japanese female with early-onset diabetes mellitus, pancreatic hypoplasia, and multiple renal cysts, harboring a novel de novo HNF1B missense variant (p.Met160Thr) located within the POU-specific domain." (PMID 42158912, 2026). "The nonsense HNF1B p.(Arg276Ter) was described in two Japanese patients with small kidneys and multiple renal cysts." (PMID 35592779, 2022).
pancreatic ductal adenocarcinoma (4 papers, 2018 to 2021). An infiltrating adenocarcinoma that arises from the epithelial cells of the pancreas. "In a recent study by Nie and colleagues, they noticed that positive HNF1B staining was found to be negatively associated with overall survival in pancreatic ductal adenocarcinoma (HR=1.54 and P=0.038)." (PMID 34150416, 2021). "They noticed that 84% of pancreatic ductal adenocarcinomas (PDAC) stained positive for HNF1B while 94% of the metastatic cases and a rather high percentage among the biliary, kidney, and ovarian stained positive for HNF1B as well." (PMID 34150416, 2021).
prostate tumors (4 papers, 2013 to 2022). "In a smaller cohort of laser-captured micro-dissected prostate tumor tissue from 36 Danish patients, we found a significant correlation between risk SNP rs3760511-G and elevated HNF1B levels (p = 0.018)." (PMID 27732966, 2016). "The results showed that HNF1B expression is greatly elevated in primary and metastatic prostate tumors compared to normal prostate gland." (PMID 36443337, 2022). "TCGA datasets show the HNF1B promoter is unmethylated in both endometrioid endometrial and prostate tumors." (PMID 25378557, 2015). "It was reported that different HNF1B isoforms were expressed in prostate tumors versus normal prostate tissue, thus providing functional evidence for a potential role of this gene in PCa." (PMID 24386569, 2013). "Moreover, we observed that the mRNA levels of HNF1B are greatly increased in localized or metastatic PCa samples and in tumors of higher grade and Gleason score, suggesting a potential function for HNF1B in advanced prostate tumors." (PMID 36443337, 2022). "Based on RNA-seq analysis of HNF1B knockdown, we next curated a panel of 25-gene as HNF1B co-expression signature and measured the degree of their expression correlation with ERG in prostate tumors." (PMID 36443337, 2022). "Furthermore, through querying multiple clinical PCa datasets, we found a positive expression correlation between FAM57A and ERG or HNF1B in prostate tumors, but not in adjacent normal prostate tissues, indicating ERG and HNF1B directed transcriptional reprogramming in human PCa tumorigenesis." (PMID 36443337, 2022).
schizophrenia (4 papers, 2017 to 2024). A major psychotic disorder characterized by abnormalities in the perception or expression of reality. "But 17q12 deletions encompassing hepatocyte nuclear factor-1beta (HNF1B) have been found to be associated with a 14-fold increased risk of suffering with ASD or schizophrenia." (PMID 33340339, 2021).
Barrett esophagus (3 papers, 2018 to 2021). Esophageal lesion lined with columnar metaplastic epithelium which is flat or villiform. "Weak nuclear with or without cytoplasmic HNF-1B expression was seen in 3 of 11 (27.3%) esophageal adenocarcinomas, 9 of 14 (64.3%) stomach adenocarcinomas, 7 of 18 bladder urothelial (38.9%), and 10 of 21 (42.8%) non-clear cell type Müllerian carcinomas." (PMID 30065837, 2018). "Together these data therefore indicate that the regulatory network involving HNF4A, GATA6, HNF1B, and FOXA transcription factors is already established in Barrett's metaplastic, is maintained in EAC cells, and HNF4A may initiate the development of Barrett's esophagus." (PMID 30962179, 2019).
carcinosarcoma (3 papers, 2015 to 2025). A malignant tumor composed of a mixture of carcinomatous and sarcomatous elements. "The KPOSE-AdCre carcinosarcoma model is WT1 and HNF1β negative, vimentin high, and shows low T-cell infiltration and no B cells or TLSs." (PMID 40642792, 2025).
clear cell ovarian tumors (3 papers, 2015 to 2025). "In addition, upregulated expression of hepatocyte nuclear factor-1β (HNF-1β) is commonly reported in ovarian clear cell tumors, including borderline tumors and carcinomas, suggesting a critical role of HNF-1β in the tumorigenesis of OCCC." (PMID 34737943, 2021). "The tumor cell expression of HNF1-β and PAX-8 serves as a highly specific immunomarker combination for ovarian clear cell neoplasms, providing cornerstone evidence for the diagnosis." (PMID 41479789, 2025).
ductal adenocarcinoma (3 papers, 2022 to 2024). "Of note hepatocyte nuclear factor-1β (HNF1B) shows a strong positive expression in clear cell pattern ductal adenocarcinoma of the pancreas." (PMID 35565450, 2022). "Particularly useful for diagnosing clear cell pancreatic carcinoma of ductal origin (exocrine) is hepatocyte nuclear factor-1β (HNF1B), which significantly shows a stronger positivity more frequently in clear cell components compared to conventional ductal adenocarcinomas." (PMID 35565450, 2022).
EAST syndrome (3 papers, 2015 to 2023). SeSAME syndrome is characterized by seizures, sensorineural deafness, ataxia, intellectual deficit, and electrolyte imbalance (hypokalemia, metabolic alkalosis, and hypomagnesemia). "Other differentials include EAST syndrome, HNF1B-associated tubulopathy and more recently described variants in CLDN10, RRAGD and mitochondrial DNA." (PMID 35585366, 2023). "This leads to hypocalciuria as occurs in GS, EAST syndrome and HNF1B-associated tubulopathy." (PMID 35585366, 2023).
electrolyte disturbances (3 papers, 2022 to 2024). "Seventeen indicators, including prenatal urogenital tract abnormalities, abnormalities of kidney or liver, electrolyte disorders and so on, were included to calculate HNF1B scores, helping to distinguish between mutated and nonmutated patients." (PMID 35346144, 2022).
endometrial tumors (3 papers, 2015 to 2020). "We also investigated the association between rs11263763 genotype and HNF1B isoform expression and usage in the TCGA endometrial tumor sample." (PMID 25378557, 2015). "Moreover, it has been reported that the single nucleotide polymorphism (SNP) of HNF1B can affect the susceptibility of endometrial tumors." (PMID 33173410, 2020). "SNP rs11263763 genotype was associated with HNF1B mRNA expression but not with HNF1B methylation in endometrial tumor samples from The Cancer Genome Atlas." (PMID 25378557, 2015).